INS (insulin)
Diseases named in the same sentence as INS in open-access papers (continued):
Sharing a sentence is not in itself a finding about the gene and the disease.
diabetes (continued). "Interestingly, the thioredoxin-interacting protein (TXNIP) was reported to regulate the miR-204-MAFA-insulin pathway contributing to glucose metabolism and diabetes progression." (PMID 29209045, 2017). "A substantial proportion of type 1 diabetes (T1D) cases present in adulthood, and despite the presence of diabetes-associated autoantibodies, the majority of these patients do not initially require insulin." (PMID 28438156, 2017). "Inaccuracies in the self-administration of insulin may adversely influence metaboliccontrol, accelerate the progression of diabetes complications, and lead todiscontinuation of treatment." (PMID 29091128, 2017). "These new insights provide an enriched understanding into the process of glucose transport and yield potential new targets for interventions aimed to improve insulin sensitivity and remediate insulin resistance, pre-diabetes, and the progression to type 2 diabetes." (PMID 29209279, 2017). "Diabetes is caused by an absolute (type 1 diabetes) or relative (type 2 diabetes) lack of insulin, and the continued hyperglycaemia due to diabetes causes abnormalities in lipid, protein, and sugar metabolism." (PMID 27927080, 2017). "While miRNAs are the drivers of several key metabolic processes associated with diabetes, such as insulin secretion and gluconeogenesis, no research has yet conclusively interconnected arsenic, miRNAs, and T2D." (PMID 28275977, 2017). "Indeed, knockout of L-type channels in mouse β cells preferentially disrupts first-phase insulin secretion, and HFD-induced diabetes in mice is associated with both reduced first-phase secretion and altered Ca2+ microdomains." (PMID 28481223, 2017). "In a previous study, it was suggested that although the mean plasma glucose and HbA1c levels indicate good control, urinary glucose excretion might be intermittently high in insulin treated diabetes patients with concomitant low plasma 1–5 AG concentrations." (PMID 28281675, 2017). "Herbal potions may accompany but be a minor aspect of a therapeutic regimen, as demonstrated clearly by Latinos with diabetes on insulin therapy." (PMID 28178991, 2017). "At the time of sample collection, all diabetic dogs were receiving treatment with exogenous insulin but were suspected to have poorly controlled diabetes based on a combination of continued clinical signs of diabetes and the results of blood and/or urine analysis." (PMID 28842637, 2017). "However, that cohort differed from ours by the long-established diabetes of its participants (mean 13.8 years, 41% receiving insulin therapy)." (PMID 28776084, 2017). "Insulin is one of the main medications used to manage diabetes." (PMID 28702089, 2017). "Diabetes mellitus (DM) is a systemic disease that is characterised by an inability of the body to either produce or effectively respond to the glucose-regulating hormone, insulin." (PMID 28956186, 2017). "Vegans in particular often had the lowest odds of diabetes when compared to other types of vegetarians; they also had lower levels of intramyocellular lipids, which may be related to insulin resistance." (PMID 28613258, 2017). "For example, pH-SKP differentiation into functional insulin-producing islet-like cells could be applied for the development of future diabetes therapy." (PMID 29141956, 2017). "However, previous studies are limited by confounders such as pre-existing diabetes or hypertension, or have used indirect measures of adiposity and insulin sensitivity (IS)." (PMID 28368024, 2017). "The lower prevalence rates in the Korean study compared to our study could be explained by study subjects’ low mean BMI (24.8Kg/ m2), exclusion of those on insulin for diabetes management and exclusion of patients with severe painful neuropathy." (PMID 28166768, 2017). "In summary, SGLT2 inhibitor was effective in diabetes mellitus as add-on to insulin therapy." (PMID 28538386, 2017). "AQP9 is down regulated by insulin in obese type 2 diabetes mellitus (T2DM) patients." (PMID 28635624, 2017).
diabetes (continued). "Moreover, many other parameters (eg insulin and leptin) were suggested to be used as indicators or predictors for diabetes status or its glycemic control." (PMID 28127544, 2017). "CE prevented dietary-induced diabetes in ApoE−/− mice by increasing the insulin secretion." (PMID 28091547, 2017). "The objective of this study was to determine whether tesamorelin, a stabilized growth hormone-releasing hormone analogue, would alter insulin sensitivity or control of diabetes." (PMID 28617838, 2017). "Moreover, ginsenosides have shown good results in the treatment of diabetes disease by improving glucose and insulin control in type 2 diabetes in a clinical trial." (PMID 29158964, 2017). "This study among type 1 diabetic children in Cameroon shows that the mother`s involvement in the diabetes management of their children and minimal/moderate caregiver involvement in the task of insulin injection are the most important determinants for good and poor glucose control respectively." (PMID 28606170, 2017). "Preoperative anemia is prevalent in patients presenting for surgery, and the odds of moderate to severe anemia is increased by older age of the patient, female gender, presence of comorbidities such as renal impairment, diabetes mellitus on insulin, congestive heart failure and higher ASA scores." (PMID 28777814, 2017). "In addition, sitagliptin can protect incretin activity, stimulate islet B-cell regeneration, improve glucose tolerance and insulin sensitivity, and delay the occurrence of diabetes." (PMID 29340105, 2017). "In a Japanese cohort study investigating the effects of insulin secretion and insulin sensitivity according to BMI on the incidence of diabetes, individuals with BMI <23.0 kg/m2 developed T2DM mainly through not insulin resistance but impaired insulin secretion." (PMID 29483484, 2017). "In the present study, insulin levels above 20 μIU/mL were potential predictors of MACE and insulin levels below that threshold were associated with risk rates for developing new cardiac events that were comparable risk rates for patients without diabetes." (PMID 28529547, 2017). "The findings derived from our study are in concordance to an earlier studies, and shows that increased insulin is not only associated with incidence of CAD, but also predicts adverse cardiac events at 1 year after coronary angiogram in type 2 diabetes mellitus." (PMID 28529547, 2017). "Maturity-onset diabetes of the young type 3 (MODY3) is a non-ketotic form of diabetes associated with poor insulin secretion." (PMID 28410371, 2017). "In addition, GGQLD improves glucose metabolism disorder, increases the insulin sensitivity index, and protects pancreatic β cells, playing a positive role in the treatment of diabetes." (PMID 29164155, 2017). "Insulin adjustment was considered part of the nurse diabetes educator’s role at that time." (PMID 28702089, 2017). "Having diabetes controlled by diet or oral antidiabetic agents seems to decrease, whereas taking insulin may increase MD." (PMID 27832382, 2017). "Encouraged by the carbohydrate–diabetes hypothesis, a plethora of studies have investigated the effect of macronutrient levels on glucose and insulin metabolism using different methodology." (PMID 29140289, 2017). "Therefore, blood glucose levels can still be maintained at normal levels, however, if β-cells fail to increase insulin secretion, diabetes will occur." (PMID 29209160, 2017). "Metformin is the major insulin sensitizer for the treatment of diabetes." (PMID 29190886, 2017). "Agents that antagonize glucagon may be of great benefit for the treatment of diabetes; however, sufficient levels of basal insulin are required for their therapeutic efficacy." (PMID 28323959, 2017). "Higher insulin levels were associated with higher CCL19, sTNFR1, amylin, and C-peptide levels on linear regression among participants who did not report a history of diabetes and with a self-reported history of diabetes on logistic regression." (PMID 28753646, 2017).
diabetes (continued). "In addition, insulin and hypoglycemic drugs affect pathogenesis of debilitating complications due to diabetes." (PMID 28975089, 2017). "Although this has not yet been confirmed through experimental glucose-clamp techniques, our data indicate that HFHC/STZ guinea pigs develop overt diabetes largely as a result of insulin resistance, which is similar to the insulin-independent state typical of human patients with type 2 diabetes." (PMID 28093504, 2017). "Arsenic and metabolites have also been shown to increase peripheral tissues' resistance to insulin, which might lead to hyperglycemia and subsequent diabetes (Frayn, 2001; Patel and Kalia, 2010)." (PMID 29285009, 2017). "However, the presence of DAA in a substantial fraction (~10%) of adults with non-insulin requiring diabetes has raised issues regarding the specificity of the antibody assays and the validity of the concept of LADA." (PMID 28829396, 2017). "In Ethiopia, investigators found that compared to non-diabetes patients, diabetic patients receiving insulin were more likely to have low weight and height (if men) and low socioeconomic status and were more likely to have been undernourished during childhood than non-diabetics." (PMID 28137307, 2017). "Recombinant human IGF-I could increase insulin sensitivity and improves glycemic control in type 2 diabetes mellitus (T2DM)." (PMID 28420208, 2017). "With respect to diabetes management, the frequency of insulin use was higher amongst the deceased patients when compared with alive patients in the patients without diabetic foot complications, at 59.79% versus 43.05%, among patients with DFU, and at 69.39% versus 58.74% among patients with LEA." (PMID 29176889, 2017). "Finally, cognitive decline and neurodegeneration has been shown to be increased not only in diabetes itself, but in pre-diabetes, in which there is insulin resistance but enough insulin is still produced to prevent overt diabetes." (PMID 28093279, 2017). "Cystathionine γ-lyase-derived H2S affects lipoprotein synthesis, insulin sensitivity, and mitochondrial biogenesis, in which tissue-specific regulation pathway might be a promising therapeutic target of diabetes and other metabolic syndromes." (PMID 28261311, 2017). "In both the liver and the kidney, glucokinase functions as a “glucose sensor”, and subnormal glucokinase activity results in the impaired control of gluconeogenesis and the failure of glucose-stimulated insulin secretion that collaborate to promote sustained hyperglycemia in diabetics." (PMID 28335416, 2017). "Insulin is the key to aiding diabetes patients in reducing blood glucose levels." (PMID 28772877, 2017). "Next, multifactorial ANOVA analysis of the serum cytokines measured in the present study was undertaken after adjustment for age, sex, WHR, BMI, duration of diabetes, creatinine and medications (insulin, sulfonylurea, metformin, GLP-1 analogues, DPP IV inhibitors, aspirin and statins)." (PMID 28794498, 2017). "When hypoglycemic episodes persist in a patient with diabetes and treatment-induced and other causes of hypoglycemia have been ruled out, an insulin-producing tumor should be considered." (PMID 28588806, 2017). "In a multivariate analysis, metformin remained significantly associated with the calcification scores, independently of age, gender, previous cardiovascular disease, eGFR-MDRD, tobacco use, diabetes duration, neuropathy, retinopathy, HbA1c, serum IL-6, and insulin prescription." (PMID 28202017, 2017). "Human induced pluripotent stem cells (hiPSCs) may provide potential resource for regenerative medicine research, including generation of insulin-producing cells for diabetes research and insulin production." (PMID 28594910, 2017). "Type 1 diabetes mellitus (T1DM) is an autoimmune disease mainly mediated by effector T lymphocytes that are activated by an autoantigen and then destroy pancreatic islets, thereby resulting in the deficiency of insulin production." (PMID 28947964, 2017).
diabetes (continued). "It is unclear whether the effects of insulin on hepatic glucose metabolism in healthy subjects apply to those observed in diabetics." (PMID 28542610, 2017). "Additionally, resveratrol reduced blood insulin levels and hyperglycemia in animal models of diabetes." (PMID 27092490, 2016). "Collectively, these results indicate that glucagon antagonism could i) be a useful adjuvant therapy in diabetes only when residual insulin action persists, and ii) help devising future β-cell regeneration therapies relying upon α-cell reprogramming." (PMID 27092792, 2016). "The app has been developed specifically to provide a phone-based platform to support the following self-management practices: bolus dose determination (based on individual insulin adjustment algorithms), diabetes diary recording, report generation and communication with health professionals." (PMID 27629774, 2016). "The finding that there is a significant reduction in biomarkers of type 1 diabetes mellitus and accompanying insulin requirements arguably supersedes the traditional paradigm that these operations are only for type 2 diabetes mellitus as they cannot reverse the inherent pancreaopathy of T1DM." (PMID 26694210, 2016). "Compared with whole-pancreas transplantation, it is a simpler operation with lower morbidity, and it has become an attractive alternative therapeutic method to conventional insulin injection or pancreas transplantation for treating diabetes and its complications." (PMID 27725943, 2016). "Although the quality of life is significantly improved in many patients, only about 1/3 of them become insulin independent, 1/3 require minimal insulin replacement (<10 u/day), and the rest develop pancreatogenic diabetes after surgery due to low islet cell survival." (PMID 26788521, 2016). "Neither diabetes mellitus nor preadmission insulin or metformin use are associated with altered disease severity, outcome or host response in patients with sepsis requiring intensive care." (PMID 27495247, 2016). "This constitutive insulin prosurvival signaling in the retina is impaired by diabetes and may contribute to neuronal degeneration in DR." (PMID 27123463, 2016). "Our study contributes novel findings in that it compares Middle Eastern and Caucasian populations that have not yet developed diabetes, but are at high risk of doing so by being insulin resistant." (PMID 27938404, 2016). "Diabetes is a disease characterized by hyperglycemia resulting from defects in insulin metabolism." (PMID 28231175, 2016). "When young children are diagnosed with T1DM, parents have complete responsibility for the daily diabetes management (assessing blood glucose levels, administering insulin, regulating food intake and guarding these parameters in conjunction with the level of physical activity) of their child." (PMID 26438336, 2016). "Twenty-five percent of the subset reported taking oral medication and/or insulin for diabetes." (PMID 26938991, 2016). "The motivation for this is to gain insight into the development of diabetes and provide insight into the answers to questions such as “does insulin resistance start in one tissue and spread to the others?” and “which tissue develops insulin resistance first?”." (PMID 27306890, 2016). "Diabetes mellitus (DM) is a metabolic disorder characterized by chronic hyperglycemia with disturbances of carbohydrate, lipid, and protein metabolism, resulting from defects in insulin secretion, insulin action, or both." (PMID 27491324, 2016). "Thus, a state of low membrane fluidity is very much diabetes-prone since it impairs insulin signaling and response." (PMID 27671740, 2016). "The skin color differences may reflect an adverse profile of parameters related to glucose homeostasis such as insulin sensitivity and secretion or higher prevalence of type 2 diabetes mellitus among minorities groups." (PMID 27626274, 2016). "Endogenous insulin secretion and beta cell function are crucial to diabetes management." (PMID 26849676, 2016).